CAPN2 (calpain 2)
Diseases named in the same sentence as CAPN2 in open-access papers (continued):
Sharing a sentence is not in itself a finding about the gene and the disease.
tumor (38 papers, 2011 to 2025). "To assess the impact of isoform‐selective pharmacological inhibition of calpain 2 on tumor metastasis, we evaluated the effects of CNa 29 in TNBC cells." (PMID 40151834, 2025). "In our xenograft tumor model, we observed increased calpain-2 expression in cSCC cells following T4O treatment." (PMID 40109860, 2025). "Our analysis revealed a hypoxic inner region characterized by nuclear HIF1α localization in three‐dimensional cultured tumor spheroids, which was notably decreased in CAPN2 knockdown tumor spheroids." (PMID 40151834, 2025). "Even after full regression (28 days postpartum), prolonged lactation maintained lower calpain-2 levels and higher expression of tumor suppressors miR-10b and miR-143/145." (PMID 41226539, 2025). "On the tissue microarray (TMA) slide containing TNBC biopsies, we observed a correlation between higher calpain 2 expression and tumor stage." (PMID 40151834, 2025). "The functional outcome of GAS2 is highly dependent on the specific substrates of Calpain-2 and cellular environment, particularly within tumor cells." (PMID 39744572, 2025). "In this study, we explored T4O’s anti-tumor activity on cSCC both in vitro and in vivo and unmasked the critical role of calpain-2 as a central effector of T4O’s antitumor actions." (PMID 40109860, 2025). "Compared to primary tumors, tumor spheroids showed increased levels of mesenchymal and HIF1α target genes, along with elevated CAPN2 expression." (PMID 40151834, 2025). "For the patients whose tumoral samples are unavailable, we are exploring reliable circulating biomarkers for evaluating the expression level of CAPN2 in tumor lesions." (PMID 39739077, 2024). "Functional assays demonstrated that METTL16 and YTHDC2 (an m6A reader) collaboratively enhanced MROH8 mRNA stability, thereby inhibiting CAPN2 expression and reducing tumor proliferation and metastasis (P<0.001)." (PMID 39434688, 2024). "METTL16 overexpression significantly inhibited tumor growth and metastasis (P<0.001) by downregulating CAPN2 through an indirect mechanism involving the transcription factor TBP and the gene MROH8." (PMID 39434688, 2024). "CAPN2 knockdown in nude mice significantly reduced tumor size and volume, while CAPN2 overexpression significantly promoted tumor growth (P<0.001)." (PMID 39434688, 2024). "Literature reports suggest that CAPN2 not only affects tumor cell proliferation but also promotes tumor metastasis." (PMID 39434688, 2024). "We further conducted limiting dilution xenograft assay, and found that CAPN2 downregulation significantly decreased tumor initiation." (PMID 39739077, 2024). "Increasing evidence have confirmed CAPN2 as a critical regulator of tumor progression, and high CAPN2 expression serves as a promising indicator for unfavorable outcomes." (PMID 39739077, 2024). "We observed that downregulation of CAPN2 not only suppressed cell proliferation, but also inhibited tumor invasion and metastasis in PC cells." (PMID 35707527, 2022). "Several studies have shown that downregulation of CAPN2 expression inhibits tumor cell growth and metastasis." (PMID 35707527, 2022). "Tandem mass spectrometric analysis presented 68 proteins were differentially expressed in LIPH‐silenced cells and LIPH‐mediated modulation of tumour cell adhesion depended on integrin‐related CAPN2 and paxillin signalling." (PMID 32618099, 2020). "Calpain-2 also plays a role in tumour and stromal cell invasion during disassembly of focal adhesions at the rear of the tumour or stromal cell." (PMID 31217905, 2019). "We describe a new localization for the ubiquitously expressed calpain-2 within nucleoli of tumor cells." (PMID 29507677, 2018).
tumor (continued). "Under constitutive activation of the pathway commonly found in CRC, calpain-2 is deregulated and tumor cells become insensitive to the extracellular microenvironment." (PMID 29507677, 2018). "Kaplan-Meier survival curve analyses were conducted to measure the correlation between CAPN2 and tumor prognosis." (PMID 29228653, 2017). "Although the mechanism of calpain in tumor progression was well elucidated, how CAPN2 regulates CRPC cell migration and invasion was little known." (PMID 28280729, 2017). "Overexpressed CAPN2 was involved in advanced tumor stage and histological grade for RCC patients, and played a crucial role in accelerating cell metastasis and proliferation." (PMID 29228653, 2017). "More recent evidences have showed the important role of CAPN2 in both carcinogenesis and tumor progression." (PMID 28280729, 2017). "Further analysis of RCC TMAs revealed that high CAPN2 staining was correlated with advanced tumor stage and high histological grade." (PMID 29228653, 2017). "CAPN2 was negatively expressed in normal kidney samples and primarily stained in cytoplasm of tumor cells." (PMID 29228653, 2017). "βig-h3 and calpain-2 promote invasion in tumor cells and they also enhance MMP secretion potential which is implicated in promoting metastasis by degradation of ECM." (PMID 22629380, 2012). "In TNBC patient tissues, elevated calpain 2 expression tended to align with higher tumor grades." (PMID 40151834, 2025). "Finally, calpain-2’s potential mediator role in T4O’s anti-tumor mechanism was investigated in calpain-2 knockdown cell lines prepared via siRNA transfection." (PMID 40109860, 2025). "Furthermore, simultaneous overexpression of METTL16 and CAPN2 significantly increased tumor cell growth and proliferation (P<0.001)." (PMID 39434688, 2024). "Additionally, the activity of tumor cells in lung metastases was significantly reduced after CAPN2 knockdown (P<0.001), indicating that CAPN2 plays a critical role in metastasis and the growth of tumor cells post-metastasis." (PMID 39434688, 2024). "Emerging evidence suggests that m6A regulators, such as METTL16, may interact with CAPN2 to influence tumor progression through post-transcriptional mechanisms." (PMID 39434688, 2024). "Our findings highlight the significance of CAPN2 in tumor regression and, thus, indicate that CAPN2 could be a promising target for PC treatment." (PMID 35707527, 2022). "Downregulated genes such as LATS2, CDC14A and CAPN2 are known tumor-suppressive molecules which could enhance cell cycle progression, cell mobility and reduce apoptosis." (PMID 34654826, 2021). "In tumour xenografts, Q8 significantly reduced expression of the angiogenic marker calpain-2." (PMID 31217905, 2019). "Previous results have shown that CAPN2 might affect the invasive and metastatic capability of tumor cells in HCC by attenuating MMPs protein levels." (PMID 28280729, 2017). "Moreover, the subsequent mechanism investigation suggested that CAPN2 promoted tumor progression by activating AKT/mTOR signaling, enhancing epithelial mesenchymal transition (EMT) and MMP9 levels." (PMID 29228653, 2017). "Similarly, knockdown of CAPN2 significantly suppressed tumor cells invasion in DU145 and PC3 compared with the NC." (PMID 28280729, 2017). "Furthermore, results demonstrated that aberrant high CAPN2 level was significantly correlated with advanced tumor stage (P = 0.011) and histological grade (P = 0.048)." (PMID 29228653, 2017). "Moreover, βig-h3, integrins and calpain-2 are known to be regulated by Ca2+, and they are also involved in tumor cell invasion." (PMID 22629380, 2012). "Downregulation of calpains after transfection with calpain-1 (μ-calpain) or calpain-2 (m-calpain) siRNA could reduce the secretion of MMPs and attenuate the adhesive and invasive potentials of some tumor cells." (PMID 22629380, 2012).
tumor (continued). "Additionally, Ki67 staining of tumor sections confirmed a significant reduction in proliferative activity after CAPN2 knockdown (P<0.001) and significantly increased proliferation with CAPN2 overexpression (P<0.01)." (PMID 39434688, 2024). "Furthermore, we explored the correlation between CAPN2 mRNA levels and clinicopathological characteristics using the TCGA-PAAD dataset and revealed that patients with PC with high CAPN2 mRNA levels showed poorer tumor grade, T stage, and tumor status than patients with PC with lower CAPN2 levels." (PMID 35707527, 2022). "In addition, CAPN2-OV could enhance N-cadherin, Vimentin and MMP9 protein level in CAKI-2 cells, which highlights the promoting role of CAPN2 in tumor metastasis in RCC." (PMID 29228653, 2017). "It is reasonable that calpain 2 may be treated as a target for limiting tumor progression." (PMID 24297527, 2014). "This study aims to elucidate the role of METTL16, an m6A writer gene, in regulating core genes such as CAPN2 and MROH8, influencing tumor growth and metastasis." (PMID 39434688, 2024). "Overall, the activity of calpain-1 and calpain-2, the two ubiquitous calpains, could be impaired by targeted treatment to impede cell transformation, suppress the enhanced motility, adhesion disassembly and the cell cycle progression, and by inducing tumor cell death." (PMID 39156707, 2024). "We observed significantly higher expression of METTL16, ITPR1, CAPN2, ITGA3, RAC1, ITGA6, and CHMP28 in tumor samples (P<0.05)." (PMID 39434688, 2024). "LIPH suppression increased the expression of FAK p397 and paxillin, two key factors in adhesion between tumour cells, suggesting that LIPH inhibits the adhesion between tumour cells and promotes EMT through CAPN2 regulation." (PMID 32618099, 2020). "CAPN2 exhibited a significant overexpression in human RCC tissues and cell lines compared with adjacent non-tumor tissues and normal human proximal tubule epithelial cell line HK-2." (PMID 29228653, 2017). "Therefore, we noted the presence of MMP7 and three calpain components, CAPN1, CAPN2, and CAPNS1, as tumor-derived EV protein cargo." (PMID 36470535, 2023). "We also found that calpain-2 is expressed by GliT cells staying inside the bulky tumour, while Gli4 cells migrating in the CC do not express calpain-2." (PMID 31601895, 2019). "We hypothesize that consistent with a starvation-insensitive feature of tumor cells, constitutively activated KRAS could prevent nucleolar accumulation of calpain-2 and therefore ribosomal biogenesis might proceed even in the absence of serum." (PMID 29507677, 2018). "In order to identify the functional role of CAPN2, we carried out silencing and overexpressing RCC cell lines to investigate its tumorigenic properties in RCC metastasis, and provided a better potential target for tumor therapy." (PMID 29228653, 2017). "Interestingly, GliT inside the tumour bulk express calpain-2, while GliT migrating away from the tumour mass do not express calpain-2." (PMID 31601895, 2019). "In addition, Western blot and immunohistochemistry analysis revealed that CAPN2 protein level was higher in tumor samples compared with that in adjacent nonmalignant tissues collected from the same patients." (PMID 28280729, 2017).
neurodegenerative disease (8 papers, 2017 to 2026). A disorder of the central nervous system characterized by gradual and progressive loss of neural tissue and neurologic function. "Active calpain-2 has been localized to protein aggregates associated with other neurodegenerative diseases, such as hyper-phosphorylated Tau protein." (PMID 36393840, 2022). "Calpain-1 and calpain-2 are ubiquitously expressed proteolytic enzymes that have been implicated in many neurodegenerative diseases and neurological disorders." (PMID 34685571, 2021). "In future studies, it will be important to ascertain how to block autophagy and ER stress by calpain-1 and calpain-2, and also to determine taurine’s therapeutic potential to treat multiple neurodegenerative diseases associated with cell death." (PMID 29036897, 2017). "The observed neuroprotective effects of calpain-2 inhibition highlight its potential as a therapeutic target for promoting neuronal repair and regeneration in neurodegenerative diseases." (PMID 40940721, 2025). "Since the activity of the calpain-2 isoform has previously been related to neurodegenerative diseases, we used immunolabeling specifically for activated calpain-2 as an additional readout." (PMID 37189329, 2023). "In the present study, we showed that Reg-1α can be cleaved in vitro by calpain-2, the calcium activated neutral protease, overexpressed in neurodegenerative diseases." (PMID 35955718, 2022). "This novel finding suggests that calpain-2 may play a role in the adaptive immune response in neurodegenerative diseases." (PMID 40940721, 2025). "Although both calpain-1 and calpain-2 are reported to be activated in neurodegenerative diseases, they may play opposite roles in cell survival and death." (PMID 36430329, 2022). "Thus, calpain-1 and calpain-2 might play opposing roles in neurodegenerative diseases." (PMID 36430329, 2022).
infection (3 papers, 2010 to 2024). The state of being infected such as from the introduction of a foreign agent such as serum, vaccine, antigenic substance or organism. "Thus, our findings show that a high expression of CAPN2 in primary human cells is associated with increased susceptibility to infection." (PMID 38349185, 2024). "In this study, we uncovered the host protease CAPN2 as a novel host factor that aides the infection of SARS-CoV-2." (PMID 38349185, 2024). "Based on the results above, CAPN2 seems to facilitate the infections of VSV-SARS-CoV-2 and SARS-CoV-2 WA1." (PMID 38349185, 2024). "SARS-CoV-2 spike protein levels as the nascent protein synthesis was first visible starting at 4 h post infection in WT cells, whereas it was barely detectable at 6 h post infection in CAPN2 KO cells." (PMID 38349185, 2024). "Calpain-2 is ubiquitinated by Nedd4, after infection with B. abortus, and degraded as intracellular calcium increases." (PMID 37143745, 2023). "To confirm the role of calpain-2 in mediating CVB infection of HBMEC, we treated cells with three known inhibitors of calpains–ALLN, calpeptin, and calpain inhibitor III—and found that they significantly reduced infection by CVB in HBMEC." (PMID 20949071, 2010).
neurological disorders (3 papers, 2021 to 2025). "This review concludes with a discussion of the potential benefits of selective calpain-2 inhibitors for the treatment of a variety of neurological disorders." (PMID 40940713, 2025).
autosomal dominant disease (1 paper, 2025). Autosomal dominant form of disease. "Decades of research indicate that calcium dysregulation is an early driver of AD pathology in both sporadic and autosomal dominant disease, with elevated calcium in the cytosol, rather than stored in the SER, activating calpain-2 to disinhibit GSK3β and cdk5 to hyperphosphorylate tau." (PMID 40365352, 2025).
CAPN2 also shares sentences with these, for which no sentence is quoted: endometriosis (2 papers); non-small cell lung carcinoma (2); abdominal aortic aneurysm (1); amelanotic melanoma (1); cardiomyopathy (1); cervical cancer (1); cystic fibrosis (1); hepatitis B virus infection (1); hereditary retinal degeneration (1); Huntington disease (1); Hypertension (1); infectious disease (1); inflammation (1); limb girdle muscular dystrophy type 2A (1); neuroblastoma (1); pancreatic adenocarcinoma (1); Parkinsonism (1); renal carcinoma (1); retinal ischemia (1); sarcopenia (1); schizophrenia (1); schwannoma (1); Seizure (1); uremia (1); uveitis (1).